KIT (KIT proto-oncogene, receptor tyrosine kinase)
Diseases named in the same sentence as KIT in open-access papers (continued):
Sharing a sentence is not in itself a finding about the gene and the disease.
tumor (continued). "Once the KIT exon 11 tumor mutant group was divided into subgroups, the statistical analysis revealed a poorer outcome for patients whose tumor had large exon 11 deletions, especially if involving codons 577-579, this may be due to the conformational change in the receptor." (PMID 21605429, 2011). "A false-negative wild type sequence in KIT exon 11 in a tumor habouring a mutation in this region could result in a wrong assessment of treatment response and for example to the change of therapy." (PMID 20598160, 2010). "Presence of phosphorylated KIT in tumor endothelia suggests that endothelial KIT is frequently activated, and thus likely binds its ligand, although the level of SCF in the endothelial cells may sometimes be below the detection threshold of immunohistochemistry." (PMID 20030644, 2010). "In addition to KIT/PDGFRA mutational status, our findings indicate that secondary chromosomal changes contribute significantly to tumor development and progression of GIST and that genomic complexity carries independent prognostic value that complements clinico-pathological and genotype information." (PMID 20470368, 2010). "Interestingly, the expression of 7 genes annotated to synaptic transmission, 15 genes annotated to blood vessel development, and 20 genes annotated to G-protein signalling were at least 2-fold higher in tumours with low KIT expression compared to those with high KIT expression." (PMID 19943934, 2009). "Tumours with tyrosine kinase receptoroverexpression have been successfully treated with targeted therapies, as ingastrointestinal stromal tumours, which express KIT and may be treated withImatinib." (PMID 18769552, 2008). "The absence of correlation between mutational status and KIT activation could be explained by the presence of SCF within tumours." (PMID 16570044, 2006). "However, the total amount of activated KIT highly varied between tumours." (PMID 16570044, 2006). "Our analysis of the activation status of KIT in 17 KIT-positive GISTs by the detection of phosphorylated tyrosine residues shows that at least a fraction of KIT was activated in each tumour, even in the absence of gain-of-function mutation, consistent with previously published data." (PMID 16570044, 2006). "GISTs with KIT mutation, particularly in exon 11, show a clearly better response to imatinib therapy as compared to tumours with no mutation, suggesting that detection of gain-of-function mutation and not solely KIT expression should be a requirement for the treatment." (PMID 15583695, 2004). "Interestingly, one patient in our series (case 8) whose tumour lacked an exon 11 KIT mutation had a partial response to imatinib by CT and a significantly reduced tracer uptake on PET." (PMID 12888812, 2003). "Immunohistochemistry is vital for establishing the diagnosis of LOT, as evidenced by tumor cell positivity for CK7 and PAX8 and negativity for CD117/KIT, vimentin, and CAIX." (PMID 41523983, 2026). "KIT-d-MMAE group displayed less intense Ki67 antigen staining, signifying a stronger anti-tumor effect." (PMID 40963922, 2025). "By simultaneously inhibiting VEGFR, FGFR, PDGFRα, RET, and KIT, LEN effectively blocks tumor angiogenesis and tumor progression, leading to potent antitumor effects." (PMID 41155549, 2025). "CD4 + ICOS + PDCD1+ (PD-1) T-cells, resembling T follicular helper (Tfh) cells were more common in HPV+ve tumours, as were CD4 + naïve-like T-cell clusters and KIT + NK-cells." (PMID 39757146, 2025). "Of the non-KIT non-PDGFRA mutated tumor samples, no models could be established." (PMID 39853155, 2025). "Immunohistochemistry staining of the tumour cells were positive for c-KIT, DOG-1, Smooth Muscle Actin, CD-117 and SDH-B." (PMID 40666070, 2025). "Animals treated with KIT-d-DM1, VcMMAE, and KIT-d-MMAE exhibited notably reduced tumor burden and slower tumor growth." (PMID 40963922, 2025).
tumor (continued). "The master transcriptional factors of MES state cells, such as c-MYC, PRRX1 and NOTCH1 were highly upregulated in the resistant tumor cells, together with the SCP marker S100B and stem cell markers KIT and SALL4." (PMID 40962798, 2025). "Proteomic changes include reduced KIT levels in both cells and EVs, suggesting that MITF regulates EV cargo to influence tumor signaling and invasion." (PMID 41168571, 2025). "Proteomic profiling further revealed its impact on multiple oncogenic and tumor-suppressive proteins, with notable upregulation of SERPINB2, KIT, and NOTCH1, alongside downregulation of COX2, DNMT1, MAPK1, AKT1, MKI67, EP300, and SMC1A." (PMID 41321870, 2025). "Imatinib-resistant tumours that harbour FGFR2 fusions or amplifications maintain phosphorylation of ERK and AKT despite complete inhibition of KIT." (PMID 41150770, 2025). "Histological analysis indicated that the KIT-d-MMAE group had smaller areas of tumor metastasis and exhibited reduced Ki67 level in tumor cells, suggesting lower proliferation rates, compared to the DPBS group." (PMID 40963922, 2025). "It specifically and durably inhibits the KIT proto-oncogene receptor tyrosine kinase (KIT) and the platelet-derived growth factor receptor A (PDGFRA), thus suppressing tumor cell growth." (PMID 40231257, 2025). "Previous research indicated effective treatment outcomes with DM1-conjugated ADCs 20, so we also synthesized a KIT-d-DM1 conjugated ApDC for in vitro and in vivo anti-tumor assessment." (PMID 40963922, 2025). "Lenvatinib is a multi-targeted tyrosine kinase inhibitor that significantly inhibits tumor angiogenesis and tumor cell proliferation by targeting signaling pathways such as VEGFR1-3, FGFR1-4, PDGFRα, RET and KIT." (PMID 41451007, 2025). "The western blot results from human and murine models consistently showed that TAMCs stimulated with the supernatants from AG‐treated tumor cells exhibited elevated expression of TAMC activation markers FcεRI and KIT." (PMID 41159485, 2025). "Simultaneous inhibition of KIT and YAP in GIST represents a promising strategy to induce apoptosis in DTPs, potentially leading to complete tumor eradication." (PMID 40921853, 2025). "Pathological examination of the resected tumor confirmed its identity as a metastatic GIST, with positive immunohistochemical staining for KIT and DOG1." (PMID 40584566, 2025). "Some studies have shown that KIT expression correlates with a favourable prognosis and that KIT, as well as other genes such as PDGFR, are expressed in more differentiated NBs and in early-stage tumours." (PMID 41511287, 2025). "It exerts its antitumor activity by inhibiting multiple receptor tyrosine kinases, including KIT, PDGFRA, PDGFRB, VEGFRs, RET and FLT3, thereby targeting both tumor cell proliferation and angiogenesis." (PMID 40733131, 2025). "Noticeably fewer PDE3A- and KIT-expressing tumor cells were detected in SC ANA-treated tumors, indicating a reduction of tumor cells as a drug response in resected tissue samples." (PMID 39930717, 2025). "By targeting the BCR-ABL tyrosine kinase and other kinases, such as c-KIT and PDGFR, imatinib directly disrupts proliferative signalling pathways critical for tumour cell survival and growth." (PMID 41426918, 2025). "In particular, FISH assays performed on tumor sections highlighted that KHSRP, even in the complexity of an in vivo model, maintains its ability to localize within the sequences of c‐KIT and c‐MYC, further underscoring the biological relevance of our findings." (PMID 39763191, 2025).
tumor (continued). "These medications target multiple kinases involved in tumor growth, angiogenesis, and metastasis, particularly vascular endothelial growth factor receptor (VEGFR), platelet-derived growth factor receptor, and c-KIT." (PMID 41235087, 2025). "Ex vivo imaging of tumors from mice injected with Cy5 labeled aptamers also indicated that KIT-d and KIT-d-MMAE have a robust capacity for in vivo tumor targeting." (PMID 40963922, 2025). "Consequently, we speculate that in the high PRTFDC1 expression group, tumor cells may be more reliant on the purine nucleotide salvage pathway to promote proliferation, rather than on the signaling pathways activated by KIT, NRAS, or KRAS mutations." (PMID 40241724, 2025). "Also in patient 3 the primary KIT exon 11 mutation could not be detected in cfDNA while the tumor volume increased from 0 to 1.75 mL at the time of PD (recurrence)." (PMID 38790141, 2024). "Targeted therapies, including inhibitors targeting BRAF, MEK, c-KIT, and NRAS, are designed to block the specific molecules responsible for tumor growth." (PMID 38399429, 2024). "Imatinib mesylate (STI571), is a selective kinase inhibitor that inhibits the activation of ALB, KIT, PDGFRA, and PDGFRB, thereby inhibiting tumor growth." (PMID 39600645, 2024). "There are some literature reports focusing on the role of KIT and TNFSF4 in the anti-tumor activity of NK cells." (PMID 39201666, 2024). "Regorafenib is an oral multi-targeted TKI, whose targets are involved in the regulation of tumor angiogenesis (VEGFR1–3 and TEK), oncogenesis (KIT, RET, RAF1, BRAF, and and BRAFV600E), and maintenance of the tumor microenvironment (PDGFRA, PDGFRB and FGFR)." (PMID 39165680, 2024). "The copy numbers of shared CNVs, such as PDGFRA/KIT, CDK4, MYC, KRAS, and VEGFR2, were highly consistent (Pearson correlation = 0.95, P = 0) between the CSF and tumor tissues." (PMID 38388726, 2024). "MYC, EGFR and KIT are among such genes with late gains in both OS and BRCA, emphasizing their ability in stimulating cell multiplication in multiple tumor types." (PMID 38448455, 2024). "In gastric GISTs, aberrant activation of KIT and PDGFRA promotes tumor growth and progression by stimulating cell cycle progression, enhancing angiogenesis, and facilitating evasion of immune surveillance mechanisms." (PMID 39064037, 2024). "Lenvatinib prevents tumor angiogenesis through inhibition of VEGFR-1, -2, and -3, and also blocks the proliferation of tumor cells through inhibition of FGFR-1, FGFR-2, FGFR-3, & FGFR-4, PDGFRα, RET, and c-KIT." (PMID 38622735, 2024). "Regorafenib, a novel oral multi-kinase inhibitor, disrupts kinases involved in tumor angiogenesis (VEGFR1, VEGFR2, VEGFR3, TIE2), tumorigenesis (KIT, RET, RAF1, BRAF, and BRAFV600E), and the tumor microenvironment (PDGFR and FGFR)." (PMID 39687893, 2024). "For example, in addition to targeting KIT and PDGFRA, imatinib has also been shown to act on host dendritic cells to enhance anti-tumour effects in vivo by promoting NK cell activation." (PMID 39070147, 2024). "In particular, combining DZNeP with venetoclax was shown to significantly eliminate CD117+ (c-KIT) AML blasts, hence indicating substantial effects on tumor stem cells." (PMID 39655332, 2024). "However, it is important to note in this study that the KIT mutation status of the tumours was not assessed, and as such, it is not possible to conclude whether the mutation had a predictive effect." (PMID 38787171, 2024). "For example, Katz’s team constructed a novel anti-KIT chimeric immune receptors (CIR) with mouse and human T cells and effectively reduced tumour growth rates in a GIST mouse model." (PMID 39070147, 2024). "It functions by inhibiting the growth of tumor cells and the formation of blood vessels through targeting various serine/threonine and tyrosine kinases such as RAF1, BRAF, VEGFR 1, 2, 3, PDGFR, KIT, FLT3, FGFR1, and RET." (PMID 37299411, 2023).
tumor (continued). "Regorafenib is an oral multi-target kinase inhibitor, which inhibits tumorigenesis, tumor angiogenesis and tumor microenvironment by targeting VEGFR1/2/3, TIE-2, BRAF, KIT, RET, PDGFR and FGFR." (PMID 36937443, 2023). "Regorafenib potently blocks several protein kinases that are involved in tumor angiogenesis (VEGFRs 1–3), oncogenesis (BRAF, RAF, RET, KIT), metastasis (FGFR, PDGFR, VEGFR3) and tumor microenvironment (TME) signaling (Tie2, CSF1R)." (PMID 37620408, 2023). "The first one constructed chimeric antigen receptor T (CAR-T) cells targeting KIT in 2013, and then demonstrated that such cells were able to produce IFNγ in vitro, lysed the cultured GIST cells and inhibit tumor growth in CDX model." (PMID 37072770, 2023). "Not only can it directly inhibit tumor growth through KIT and FLT-3 inhibition of RAF/MEK/ERK signaling pathway, but also indirectly blocking tumor angiogenesis by blocking VEGFR and PDGFR with a dual anti-tumor effect." (PMID 37803421, 2023). "The third one got cytokine-induced killer cells (CIKs) from KIT/PDGFRA-WT GIST patients in 2022, and found that patient-derived CIKs killed autologous imatinib- and sunitinib-resistant tumor cells either directly or indirectly." (PMID 37072770, 2023). "When tumor tissue exhibited low CBX7 expression, the infiltration of quiescent mast cells (marked by KIT) in the tumor center was significantly inhibited." (PMID 37189494, 2023). "Regorafenib is an oral multi-kinase inhibitor that targets signaling pathways involved in tumor angiogenesis (VEGFR1-3 and TIE2), oncogenesis (KIT, RET, RAF1, and BRAF), and the tumor microenvironment (PDGFR, FGFR, and CSF1R)." (PMID 37869085, 2023). "Sorafenib has tumor-agnostic efficacy in patients with tumors harboring genomic alterations in PDGFRA/B, VEGF-Rs, Flt-3, KIT, FGFR1 or the RAF/MEK/ERK pathway." (PMID 37444551, 2023). "The KIT gene plays critical roles in tumor cell activity, but AML vaccines targeting KIT have yet to be explored." (PMID 37513844, 2023). "It is important to know the effects of these antiangiogenic drugs not only on the tumour but also on the TME, for example, sunitinib decreases MDSCs expansion due to the inhibition of the VEGF and c-KIT pathways." (PMID 37396098, 2023). "The large proportion of tumours in our study with aberrant KIT patterns and Ki67 counts above the threshold were an unexpected finding, and suggest that despite the fact that many of the tumours were histological low-grade tumours, digital MCT might be prognostically unfavourable." (PMID 37238124, 2023). "Next, to explore the impact of CXCL16 NAb on lineage dynamics of tumor-infiltrating lymphocytes (TILs), we looked into percentages of CD45.1+ progenitor-like c-KIT+LIN-, Cluster 0-like CD11bhighPD-L1high, and CD11chigh I-A-I-Ehigh DCs (gating strategy)." (PMID 37055410, 2023). "KIT, CD34, THY1, and EPCAM were expressed in large vessel structures and tumor capsules from patients #4001 and #3559." (PMID 37932266, 2023). "Binase has proven to be a promising agent that induces apoptosis in a number of tumor cells expressing RAS, KIT, and AML/ETO oncogenes and also suppresses tumor metastasis in animals." (PMID 36674440, 2023). "The inhibition of VEGFR2 and VEGFR3 also contributes to the remission of tumor metastasis through antiangiogenic and antiproliferative mechanisms, while the inhibition of RAF-1, RET, and KIT pathways leads to reduced cell proliferation and increased apoptosis." (PMID 38068319, 2023). "MBP-11901, a multi-RTK inhibitor, was shown to inhibit tumor growth and kill HCC by targeting VEGFR2, c-KIT, PDGFRβ, and FLT3." (PMID 35454900, 2022). "In previous work, we showed that silencing of SH3BP2 diminished KIT, PDGFRA, and MITF levels lead to a reduction in tumor growth in vitro and in vivo." (PMID 36551682, 2022).
tumor (continued). "Particularly, the combination of DZNeP with Ven dramatically eliminated CD117 (c-KIT) (+) AML blasts, suggesting the effect of the combination on tumor stem cells." (PMID 36232694, 2022). "Regorafenib inhibits kinases and cellular pathways involved in angiogenesis and tumor growth, such as the VEGFR1-3, FGFR1-2, c-KIT, PDGFRα/β, RET, and BRAF." (PMID 36612019, 2022). "It is a multikinase inhibitor targeting VEGFR1-3, MET, the TAM family of kinases (TYRO-3, AXL, MER), RET, ROS1, KIT, TRKB, FLT-3, and TIE-2, which are mostly involved in tumor growth, angiogenesis, and immune regulation." (PMID 36612019, 2022). "Genomic DNA from FFPE tumor samples and paired blood samples were extracted by QIAamp DNA FFPE Tissue KIT and QIAamp DNA Blood Midi KIT (Qiagen, Dusseldorf, Germany) following the manufacturer’s instructions, respectively." (PMID 35765075, 2022). "We previously reported that silencing of SH3BP2 leads to a reduction of KIT expression at both mRNA and protein levels, as well as MITF at the protein level, resulting in a decrease in GIST tumor growth in vitro and in vivo." (PMID 36551682, 2022). "Our findings support a model in which KIT stimulates TGFβ expression to promote stroma formation and activation—resulting in CRC progression —while simultaneously protecting the tumor cells against TGFβ-induced growth inhibition through suppression of SMAD2." (PMID 35842424, 2022). "Regorafenib can inhibit a variety of kinases involved in angiogenesis, cell proliferation, and tumor growth as well as the tumor microenvironment, mainly including VEGFR1∼3, KIT, RET, PDGFR-β, and FGFR." (PMID 37251557, 2022). "Sorafenib inhibits angiogenesis and tumour progression by limiting the effects of various receptor tyrosine kinases such as VEGFR-2, VEGFR-3, c-KIT, or platelet-derived growth factor receptor beta (PDGFRβ)." (PMID 35954446, 2022). "The modified PDOs were then used in in vitro and in vivo assays to study how KIT regulates various aspects of CMS4 CRC, including tumor stroma formation, TGFβ signaling, and EMT." (PMID 35842424, 2022). "Again, nobiletin was demonstrated to induce antileukemic effects through the down-regulation of c-KIT gene in THP-1 cells, while treatment with diosmetin delayed tumor growth in AML mouse xenografts." (PMID 36297603, 2022). "The microarrays which screened tumour-specific circRNA profiles of GIST, identified a GIST-specific circRNA-miRNA-mRNA regulatory network related to KIT, which showed the potentials of circRNAs in the drug resistance of GIST by targeting KIT." (PMID 35174150, 2022). "Pazopanib limits tumor growth by targeting angiogenesis via the inhibition of VEGFR, PDGFR, c-KIT, and FGFR." (PMID 35785151, 2022). "First-generation TKIs are multi-target inhibitors that include the four main isoforms of FGFR and other signaling proteins of the tumor microenvironment, such as VEGFR, KIT, and RET." (PMID 35054474, 2022). "In the tumour cells, cabozantinib interrupts VEGFR1/VEGFR2/c-KIT/TIE2 pathways, downregulating angiogenic factors (HIF1α, VEGFA) and vascular remodelling factors (MMP2, MMP9)." (PMID 35106125, 2022). "In patients with metastatic progressive KIT-mutant GIST, tumor burden (as measured by the average diameter of the 3 largest lesions) was higher with detectable KIT ctDNA mutation than in those without (median, 5.97 cm vs. 2.40 cm, p = 0.0195)." (PMID 35273917, 2022). "Vascular endothelial growth factor receptor 2 (VEGFR2), platelet-derived growth factor receptor beta (PDGFR-β) and v-kit cellular homologue (c-KIT) are receptor tyrosine kinases (RTK), whose expression has been reported in multiple canine tumours." (PMID 35324835, 2022). "Another kinase inhibitor, Sorafenib (SOR), acts by inhibiting several different kinases (RAF-1, VEGF, c-KIT, PDGFR, ERK, and FLT3) involved in tumor cell proliferation and angiogenesis." (PMID 35053339, 2022).